ZNF767P (zinc finger family member 767, pseudogene)
Synonyms: FLJ12700; formerly ZNF767
Gene: Transcribed unprocessed pseudogene on chromosome 7 (149,619,924 to 149,624,565, reverse strand). Ensembl gene ENSG00000133624.
Diseases named in the same sentence as ZNF767P in open-access papers:
ZNF767P is named in the same sentence as 3 diseases in open-access papers, as found by Europe PMC text mining. Sharing a sentence is not in itself a finding about the gene and the disease. The quoted sentences say what the papers report.
colon cancer (1 paper, 2023). "In the present study, a four-gene signature of colon cancer, consisting of HSF4, UPK3B, ZNF767P, and AGAP9, was generated and validated." (PMID 36681801, 2023).
cancer (1 paper, 2022). A tumor composed of atypical neoplastic, often pleomorphic cells that invade other tissues. "ZNF767P, a pseudogene on chromosome 7, has been reported to be differentially expressed in human cancers and to be translated when fused with oncogenic genes (e.g., BRAF)." (PMID 35712126, 2022).
ZNF767P also shares sentences with these, for which no sentence is quoted: colon adenocarcinoma (1 paper).